FOXP3 (forkhead box P3)
Diseases named in the same sentence as FOXP3 in open-access papers (continued):
Sharing a sentence is not in itself a finding about the gene and the disease.
colon carcinoma (continued). "Gene and protein analysis of tumor tissues from patients with CRC was performed to quantify the expression of Foxp3 in tumor infiltrating Treg and colon cancer cells." (PMID 23382847, 2013). "Multivariate Cox regression analysis demonstrated lymph node metastasis (N category) and Foxp3 expression in colon cancer cells as significant prognostic parameters of survival in human CRC." (PMID 23382847, 2013). "The stepwise procedure kept in the model the N category and Foxp3 expression in colon cancer cells as prognostic parameters (Chi-quadrat statistics, p<0.01)." (PMID 23382847, 2013). "We analyzed the expression and location of infiltrating cytotoxic CD8+ T cells and FoxP3+ regulatory T cells within colon carcinomas." (PMID 22879926, 2012). "Increased numbers of FoxP3+ Tregs have been detected in colon cancers compared to surrounding unaffected mucosa." (PMID 22879926, 2012). "The prognostic impact of FoxP3+ and CD8+ T cell density are inter-dependent, whereby FoxP3+ exerts a favorable influence on survival only in colon cancers with low CD8+ infiltration." (PMID 22879926, 2012). "Moreover, Treg marked by FoxP3 showed potent positive prognostic factor in colon cancer (p = 0.0046), which recapitulated the previous report." (PMID 38557819, 2024). "Furthermore, a higher FoxP3+ T-lymphocyte tumor infiltration score has been proven to be a favorable prognostic factor in patients with colon cancer undergoing chemotherapy or chemoimmunotherapy." (PMID 37958412, 2023). "Also, oral administration of Curcumin for one month in patients with advanced colon cancer significantly reduced FoxP3 expressing Tregs and increased T-bet expressing Th1 in the peripheral blood." (PMID 38008819, 2023). "Interestingly, FoxP3+ T cells only have a positive effect on survival in colon tumors that have low levels of CD8+ T-cell infiltration." (PMID 35655158, 2022). "Therefore, FOXP3 expression in different T cell subsets determines a good prognosis in patients with colon cancer." (PMID 35003370, 2021). "Liver metastasis from colon cancer was associated with a higher intratumoural CD8/CD3 ratio (73.5% vs. 52.3%, p = 0.011), peritumoural CD8/CD3 ratio (72.6% vs. 54.9%, p = 0.035), and peritumoural Foxp3/CD3 ratio (77.8% vs. 55.8%, p = 0.013) than rectal cancer." (PMID 31810350, 2019). "A recent study using reciprocal bone marrow chimeras in a mouse model of sporadic colon cancer, genetic ablation of ST2 in both hematopoietic and non-hematopoietic compartments leads to increased tumor-infiltrating ST2+ Foxp3+ Tregs and enhanced colon tumor development." (PMID 30483263, 2018). "Further, we measured the expression of FOXP3 in colon tumor tissues and normal colonic tissues." (PMID 30013992, 2018). "To further explore the biological functions of FOXP3 in the progression of cancer, we analyzed the whole transcriptome data on bladder cancer and colon cancer from the GEO database and found that the differentially expressed genes were associated with blood vessel-related events." (PMID 29970908, 2018). "To investigate whether the FOXP3-TSDR was aberrantly DNA methylated in CD4+ T cells from colon tumor tissues, we did bisulfate sequencing analysis for TSDR." (PMID 30013992, 2018). "Next, we infected colon cancer cell HT29 with FOXP3 overexpression or interference viruses." (PMID 28591725, 2017). "Our in vivo study showed that As2O3 could significantly reduce local infiltration of Tregs and Foxp3 expression, which suggested that As2O3 inhibited lung metastasis of colon cancer via selectively reducing the infiltration of Tregs." (PMID 27677289, 2016). "Importantly, we showed that As2O3 reduced the infiltration of Tregs and suppressed the expression of Foxp3 in lung metastases of colon cancer." (PMID 27677289, 2016). "Quantitative Real Time PCR analysis of Foxp3 expression in colon cancer cell lines." (PMID 23382847, 2013).
colon carcinoma (continued). "Our objective was to examine the prognostic impact of tumor-infiltrating FoxP3+ regulatory T cells (Tregs) in relation to cytotoxic CD8+ T lymphocytes in patients with colon carcinomas characterized by DNA mismatch repair (MMR) status who participated in adjuvant chemotherapy trials." (PMID 22879926, 2012). "Recently a new CD8+CD25+Foxp3+ (T8reg) T cell subset was described in patients with colon cancer." (PMID 20205946, 2010). "FOXP3 induction was titratable, in that increasing the dose of cancer supernatant from 12.5 to 25%, and again to 50% of the total culture media leads to greater increases in FOXP3 expression in the naïve T cells, particularly for supernatants representing colon cancers." (PMID 28239749, 2017). "Given data suggesting that interactions among T lymphocyte subsets may regulate the host-mediated anti-tumor reaction, we examined the association of FoxP3+ and CD8+ T cells with patient prognosis in stage II and III colon cancers from participants in adjuvant chemotherapy studies." (PMID 22879926, 2012). "In a colon cancer study, deleting the ST2 gene in mice led to the infiltration of ST2+FoxP3+Tregs in tumors, promoting the development of colon cancer." (PMID 39925809, 2025). "Given that USP47 correlated with the Treg signature in human CRC and GC tissues, we inoculated Usp47+/+Foxp3-Cre and Usp47fl/flFoxp3-Cre mice with MC38 murine colon cancer cells to examine the functional importance of USP47 in tumor-infiltrating Tregs." (PMID 37788092, 2023). "Taken together, these data show that, in the context of inflammation, dysfunctional CD8+ T cells, together with Foxp3+ Tregs and γδT17 cells, contribute to the immunosuppressive TME in colon tumors from ApcMin/+; p16cis/cis mice." (PMID 37143122, 2023). "For every individual image of our colon cancer relapse dataset, we calculated the total number of T cells (CD3+) and regulatory T cells (CD3 + FoxP3 + CD8−) to investigate the potential change in a dense and a rare cell population, respectively." (PMID 36466076, 2022). "These analyses showed that the Foxp3 mean fluorescence intensity (MFI) ratio between CD39+ and CD39− intratumoral Treg was greater in colon tumors of patients from group I, with high CD39 expression, compared to Treg from group II with low CD39 expression." (PMID 34407765, 2021). "Reportedly, Treg cells (CD8+ FOXP3+) have a neglected but strong suppressive effect on the immune system in colon cancer, but the function of Treg cells (CD8+ FOXP3+) in LSCC is less widely studied." (PMID 33816462, 2021). "In colon cancer, the results revealed strong evidence that CD8+, FOXP3+, and CDRO45+ T cell are correlated with increased DFS." (PMID 31118034, 2019). "To further explore the biological functions of FOXP3, we analyzed the whole transcriptome data (control cells vs. FOXP3-overexpressing cells) for bladder cancer (GSE81157) and colon cancer (GSE71980) from the Gene Expression Omnibus (GEO) database." (PMID 29970908, 2018). "The results showed that FOXP3 mRNA and protein levels were sharply increased in CD4+ T cells from colon tumor tissues." (PMID 30013992, 2018). "Taken together, we here revealed possible involvement of FOXP3 in regulating cCSC self-renewal via tuning COX2 expression, and thus providing a new target for the eradication of colon cancer stem cells." (PMID 28591725, 2017). "Our study here revealed a negative regulatory role of FOXP3 in tuning the self-renewal of cCSCs by inhibiting COX2 expression, which provides a new target and strategy for the removal of colon cancer stem cells." (PMID 28591725, 2017). "In this study, we aimed to investigate the correlation between the demethylation status of FOXP3-TSDR and the clinicopathological features of Chinese patients with colon cancer." (PMID 24938080, 2014).
colon carcinoma (continued). "To confirm the Foxp3 expression in tumor cells we performed RT-qPCR, FACS analysis and immunofluorescence double staining analyses in different human colon cancer cell lines (SW480, SW620, and HCT-116)." (PMID 23382847, 2013). "FoxP3+ and CD8+ densities in tumor epithelial and stromal compartments were analyzed by immunohistochemistry and quantified in resected, stage II and III colonic carcinomas (N = 216)." (PMID 22879926, 2012). "In conclusion, we found that the prognostic impact of FoxP3+ and CD8+ T cell density are inter-dependent, whereby FoxP3+ exerted a favorable influence on survival only in colon cancers with low CD8+ infiltration." (PMID 22879926, 2012). "In this study, we determined the density of FoxP3+ and CD8+ T lymphocytes in epithelial and stromal compartments of human colon cancers, and their relationship to MMR status and patient survival rates." (PMID 22879926, 2012). "In this study, we found that the ratio of GUDCA to UDCA in both RCC and LCC colon tumors was positively correlated with FoxP3 + Treg cell levels but was not significantly correlated with CD8 + T cells." (PMID 36274154, 2022). "Immunohistochemistry showed significantly higher CD3, CD3-IL17, FoxP3, and RORγT cells in colon cancer, but not in adenomatous-tissues as assessed by immune-stained cell counts." (PMID 34804993, 2021). "In human colon cancers (based on The Cancer Genome Atlas (TCGA) data), the expression of endogenous PP2A inhibitors, CIP2A and SET, correlated positively with the infiltration of CD8+ T cells and CD20+ B cells and negatively with FOXP3+ Treg cells." (PMID 34911954, 2021). "Notably, more than 30% of CD4+ FOXP3+ Tregs in colonic tumors of BALB/c mice expressed ST2, versus 3% of CD4+ FOXP3- T cells, thus indicating that ST2 expression in the CD4+ T cell compartment was mainly restricted to FOXP3+ Tregs." (PMID 31165767, 2019). "Using flow cytometry analyses of cells from 46 colon cancer patients, we confirm the accumulation of CD39+ Treg in the tumor tissue compared to unaffected colon tissue, and also show that tumor-infiltrating Treg express more CD39 and Foxp3 on a per cell basis." (PMID 30651930, 2018). "Moreover, we also found that the expression of STAT5 and TET2 was increased in CD4+ T cells from colon tumor tissues, and the superfluous STAT5 and TET2 binding to FOXP3-TSDR resulted in DNA hypomethylation." (PMID 30013992, 2018). "All of these data indicate that FOXP3 and COX2 might involve in the regulation of the stemness of colon cancer stem cells." (PMID 28591725, 2017). "It has been demonstrated previously that IFN-γ can induce activation and expansion of MDSCs in colon cancer, and that activated MDSCs not only inhibit effector T cell activity/proliferation but also induce immunosuppressive CD4+CD25+Foxp3+ TReg cells from CD4+CD25− T cells." (PMID 22496728, 2012). "Interestingly, we have also observed a decrease in Foxp3 in DLD1 colon cancer cells in vitro (unpublished data), suggesting that the effect of FTS on cancer cells that express Foxp3 might be more general than previously supposed." (PMID 22323550, 2012). "By comparing paired tumor and adjacent normal tissue samples from 24 individuals with colon cancer, we found transcript levels for the IL-23-specific subunit IL23A and FOXP3 were both elevated in tumor tissue compared to adjacent normal tissue." (PMID 38375204, 2023). "Others claimed that FOXP3+ T cells was a favorable prognostic factor in CRC and colon cancer or was not an independent prognostic factor of CRC." (PMID 25875774, 2015).
glioma (85 papers, 2008 to 2025). A benign or malignant brain and spinal cord tumor that arises from glial cells (astrocytes, oligodendrocytes, ependymal cells). "A transcriptomic study showed that Foxp3 expression increases with the aggressiveness of gliomas and is associated with poor survival in TCGA and Moroccan patients." (PMID 37274252, 2023). "Through bioinformatic analysis, low expression of cyclin G2 has been implicated with high expression of Foxp3 and poor prognosis in glioma." (PMID 34452627, 2021). "CD4+ and perivascular Foxp3+ TILs associate with tumor angiogenesis and tumor progression in glioma patients." (PMID 29163521, 2017). "Accumulation and activation of CD4+FoxP3+ Tregs acts as a dominant immune escape mechanism for gliomas and underline the importance of controlling tumor-infiltrating Tregs in glioma immunotherapy." (PMID 24202450, 2013). "Although CD4+ cell numbers alone do not directly correlate with clinical outcome in GBM patients, new evidence suggests that elevated CD4+ and/or CD4+FOXP3+ population ratios may be indicative of glioma disease severity and risk of recurrence." (PMID 32914058, 2018). "Our results imply that PD-1 and FOXP3 expressions in glioma infiltrating lymphocytes play a significant role in the progression of the tumor into high-grade neoplasm and may be linked to the biological malignancy of high-grade glial tumors." (PMID 37621817, 2023). "Dysbiosis, in particular, can downregulate the expression of forkhead box P (Foxp3) in the brain, contributing to glioma development." (PMID 40075568, 2025). "The strong correlation between HO-1 expression and CD4+ CD25+ FoxP3+ Treg infiltration suggests that HO-1 plays a role in FoxP3-mediated immune suppression during the progression of gliomas." (PMID 40514725, 2025). "Remarkably, studies have shown that FOXP3 can regulate the expression of ARHGAP15 in glioma, with significant correlations between ARHGAP15 expression and glioma severity." (PMID 39075640, 2024). "In dogs, FoxP3 expression was described in several tumors, such as gliomas and histiocytic sarcomas." (PMID 38672372, 2024). "The results also suggest it is possible that both PD-1 and FOXP3 will emerge as novel glioma molecular markers and therapeutic targets." (PMID 37621817, 2023). "In this study, we systematically investigated the expression profiles of PD-1 and FOXP3 in TILs of astrocytic and oligodendroglial lineages of gliomas." (PMID 37621817, 2023). "It was also reported that FoxP3 overexpression favors apoptosis of glioma cells; it also considerably enhances the induction of apoptosis by TNF-a or chemotherapeutics." (PMID 37274252, 2023). "Eleven cases (25.58%) of high-grade gliomas exhibited high FOXP3 expression, with high staining pattern centering the perivascular area in the majority of the cases." (PMID 37621817, 2023). "This study aims to investigate the extent of immunosuppression in glial tumors by analyzing the clinical significance of the expressions of PD-1 and FOXP3 in gliomas." (PMID 37621817, 2023). "This dysregulation of the gut flora can also reduce Foxp3 levels in the brain, worsening glioma progression." (PMID 37943609, 2023). "We constructed a univariate and multivariate cox regression analysis based on ICD-DEGs to identify three genes (FOXP3, MYD88 and IL6) associated with prognosis of glioma patients." (PMID 37456890, 2023). "Then, we evaluated the effect of GM on the expression of CD8 and Foxp3 in the glioma microenvironment." (PMID 35345443, 2022). "Foxp3+ Tregs have been extensively studied in gliomas and frequently infiltrate high-grade malignant gliomas." (PMID 35646697, 2022). "The accumulation of CD4+CD25+Foxp3+ Tregs is one of the hallmark features of GBM, and Tregs have been the predominant targets for immunotherapy in glioma models and patients." (PMID 35029050, 2022).
glioma (continued). "Overall, our results suggest that maintaining a balanced and stable gut microbiome environment in mice can upregulate Foxp3 expression in the brain to slow down the development of glioma." (PMID 35345443, 2022). "We also demonstrated that antibiotic treatment led to gut microbiome dysbiosis, downregulated the Foxp3 expression in mouse brain, and promoted glioma development in mice." (PMID 35345443, 2022). "The results of IHC showed that compared with the normal brain tissues, Foxp3+ cells (Foxp3+Treg/CD4+ T cells) were increased significantly in the glioma tissues while T-bet+ cells (T-bet+Th1/CD4+ T cells) were significantly reduced." (PMID 35181676, 2022). "Maintaining the balance of the gut microbiome microenvironment can upregulate Foxp3 expression in mouse brain and delay glioma development." (PMID 35345443, 2022). "FoxP3+ Treg infiltration was observed in 17 cases of glioma, mostly in high-grade gliomas (9 GBM, 7 WHO grade 3, and 1 WHO grade 2)." (PMID 35646697, 2022). "Forkhead box P3 (FOXP3)+ tumor-infiltrating lymphocytes (TILs) were associated with tumor angiogenesis and tumor progression in glioma patients." (PMID 36429083, 2022). "A balanced environment of GM can upregulate the expression of Foxp3 in the brain and delay the development of glioma." (PMID 35345443, 2022). "The Spearman correlation analysis results suggested that the immune marker sets of Treg (FOXP3, CCR8, TGFβ1), TAM (CCL2, CD68, IL-10), and MDSC (CD33, ITGAM, FUT4) were significantly associated with the PROS1 expression in glioma." (PMID 36685506, 2022). "The present study came to similar conclusions; however, some FoxP3+ Treg infiltration was still observed in grade 3 gliomas and oligodendroglial tumors." (PMID 35646697, 2022). "Next, we detected the expression of CD8 and Foxp3 in mouse brain tissues to explore the effect of gut microbiome dysbiosis on the glioma microenvironment." (PMID 35345443, 2022). "Maintaining the balance of GM in mice can upregulate Foxp3 expression in brain and slow down glioma growth." (PMID 35345443, 2022). "Our results have proved that the gut microbiome dysbiosis in mice can lead to the decrease of Foxp3 expression in the glioma microenvironment and promote the development of glioma, further indicating that GM have a certain effect on adaptive immunity." (PMID 35345443, 2022). "Analysis of the TCGA database for glioma patients revealed a significantly positive association between CD133 and Foxp3, the specific marker for Tregs." (PMID 33576874, 2021). "In this study, we first performed an immunohistochemical examination for Foxp3 of tissue microarray slides of 72 high-grade glioma patients and analyzed the patients’ survival time." (PMID 33429364, 2021). "Foxp3+ Tregs are considered to constitute an essential part of the immunosuppressive microenvironment of gliomas." (PMID 33429364, 2021). "Consistently, we observed a positive correlation between CD133 and Foxp3 in our clinical glioma samples." (PMID 33576874, 2021). "The degree of variability in the available literature on the impact of T-regulatory cells on OS of glioma patients, alongside the increased FoxP3 levels in methylated compared to unmethylated tumour core, signifies the need for further investigation." (PMID 33995529, 2021). "Foxp3+ regulatory T cells (Treg) play an important part in the glioma immunosuppressive microenvironment." (PMID 33429364, 2021). "Foxp3+ regulatory T cells (Treg) play an important role in the glioma immunosuppressive microenvironment." (PMID 33429364, 2021). "Since this work, there has been an increased focus on the contributions of CD4+ Th cells and subset CD4+FOXP3+ Tregs to glioma progression at both the pre-clinical and clinical levels." (PMID 32914058, 2018). "On the other hand, ARHGAP15 is reported to be regulated by transcription factor forkhead box P3 (FOXP3) in glioma cells." (PMID 29534468, 2018).